INTS11 (integrator complex subunit 11)
Description:
RNA endonuclease component of the integrator complex, a multiprotein complex that terminates RNA polymerase II (Pol II) transcription in the promoter-proximal region of genes. The integrator complex provides a quality checkpoint during transcription elongation by driving premature transcription termination of transcripts that are unfavorably configured for transcriptional elongation: the complex terminates transcription by (1) catalyzing dephosphorylation of the C-terminal domain (CTD) of Pol II subunit POLR2A/RPB1 and SUPT5H/SPT5, (2) degrading the exiting nascent RNA transcript via endonuclease activity and (3) promoting the release of Pol II from bound DNA. The integrator complex is also involved in terminating the synthesis of non-coding Pol II transcripts, such as enhancer RNAs (eRNAs), small nuclear RNAs (snRNAs), telomerase RNAs and long non-coding RNAs (lncRNAs). Within the integrator complex, INTS11 constitutes the RNA endonuclease subunit that degrades exiting nascent RNA transcripts. Mediates recruitment of cytoplasmic dynein to the nuclear envelope, probably as component of the integrator complex.
Synonyms: Int11; RC-68; CPSF3L; RC68; FLJ20542; CPSF73L; NEDMLOB; PSF3L
Tractability: PROTAC: UniProt records ubiquitination sites on it; ubiquitination databases record sites on it.
Gene: Protein-coding gene on chromosome 1 (1,311,585 to 1,324,687, reverse strand). Ensembl gene ENSG00000127054.
Subcellular location: Nucleus; Cytoplasm
Subcellular location (Human Protein Atlas): Cytosol; Nucleoplasm
Pathways (Reactome):
Gene expression (Transcription): RNA polymerase II transcribes snRNA genes
Gene Ontology:
Molecular function: protein binding; RNA endonuclease activity
Biological process: regulation of transcription elongation by RNA polymerase II; RNA polymerase II transcription initiation surveillance; snRNA 3'-end processing; snRNA processing
Cellular component: blood microparticle; cytoplasm; cytosol; INTAC complex; integrator complex; nucleoplasm; nucleus
Genetic constraint (gnomAD): Loss-of-function variants: 77 observed, 76.1 expected, observed/expected ratio (o/e) 1.01, 90% interval 0.84 to 1.22. The synonymous counts are far from expectation, so gnomAD's model fits this gene poorly and the ratio says little. Missense variants: 875 observed, 804.92 expected, observed/expected ratio (o/e) 1.09, 90% interval 1.03 to 1.15. Synonymous variants: 441 observed, 315.33 expected, observed/expected ratio (o/e) 1.4, 90% interval 1.29 to 1.51.
Homologues: Orthologues: chimpanzee INTS11 (98% identical), dog INTS11 (98% identical), mouse Ints11 (97% identical), guinea pig INTS11 (96% identical), rat Ints11 (96% identical), macaque INTS11 (95% identical), pig INTS11 (95% identical), tropical clawed frog ints11 (90% identical), zebrafish ints11 (84% identical), Drosophila melanogaster IntS11 (68% identical), Caenorhabditis elegans ints-11 (57% identical). Paralogues in human: CPSF3 (36% identical), CPSF2 (24% identical), INTS9 (17% identical).
Diseases named in the same sentence as INTS11 in open-access papers:
INTS11 is named in the same sentence as 14 diseases in open-access papers, as found by Europe PMC text mining. Sharing a sentence is not in itself a finding about the gene and the disease. The quoted sentences say what the papers report.
B-cell acute lymphoblastic leukemia (1 paper, 2024). A neoplasm of lymphoblasts committed to the B-cell lineage, typically composed of small to medium-sized blast cells. "Additionally, it was identified as a germline susceptibility locus in childhood precursor B-cell acute lymphoblastic leukemia INTS11 in zebrafish knockdowns resulted in hematopoietic dysfunction and inducing the formation of adipose cells." (PMID 38926181, 2024).
viral infection (1 paper, 2025). "We next evaluated if INTS11 would be recruited to the human genome differently under latent and lytic viral infection." (PMID 40801543, 2025). "In contrast to viral genes, only selective sets of human genes were either upregulated or downregulated by INTS11 under each condition, which agrees with the previous reports on INTS11’s role in the human transcriptome without viral infection." (PMID 40801543, 2025). "INTS11 ChIP-seq signals peak in two hotspots on the KSHV genome, which could be crucial for the role of the integrator complex during viral infection." (PMID 40801543, 2025).
tumor (5 papers, 2014 to 2025). "We demonstrated that depletion of INTS11 decreased the transcription of Notch target genes in EAC leading to tumor growth failure." (PMID 34551776, 2021). "Disruptions in this balance, such as through mutations in INTS6 or INTS11, lead to aberrant transcriptional elongation, resistance to CDK9 inhibition, and amplified oncogenic transcriptional responses, linking the INTS complex to both transcriptional regulation and tumor susceptibility." (PMID 40966122, 2025). "To evaluate whether INT is required for Notch-driven tumor growth in vivo, we inoculated nude mice with OE33 cells harboring a doxycycline-inducible shRNA against INTS11 and allowed tumor formation." (PMID 34551776, 2021).
cancer (3 papers, 2017 to 2021). A tumor composed of atypical neoplastic, often pleomorphic cells that invade other tissues. "We next asked whether INTS11 knockdown affects the MAPK-mediated responsiveness in cancer cell lines with activating mutations in the MAPK signaling pathway." (PMID 28982763, 2017). "INTS9, INTS11, INTS13, and INTS14 were mutated in very few cancer types, with a very low mutation rate." (PMID 28468258, 2017). "We compared the effectiveness of MEK and ERK1/2 inhibitors with INTS11 knockdown for cellular growth suppression in multiple cancer cell lines." (PMID 28982763, 2017). "As the downregulation of Notch has been associated with cell growth inhibition and stimulation of apoptosis in various types of cancer, we sought to further determine whether the INTS11 depletion results in apoptosis in EAC via flow cytometry." (PMID 34551776, 2021). "Furthermore, inactivation of either NACK or INTS11 results in the abrogation of Notch-dependent transcription in cancer cells leading to cell growth arrest, and INTS11 knockdown results in G2/M arrest and apoptosis." (PMID 34551776, 2021). "Additionally, INTS11 knockdown diminishes the MAPK responsiveness and cellular growth in A375 and A549, cancer cell lines with activating mutations in BRAF and KRAS, respectively." (PMID 28982763, 2017). "Importantly, depletion of INTS11 diminishes cellular proliferation in A375 cells rendered resistant to MAPK inhibitors, highlighting a possible avenue to overcome drug resistance by targeting INTS11 in cancer cells." (PMID 28982763, 2017). "The identification of Integrator, especially its catalytic subunit, INTS11, as a critical downstream component of this pathway opens the way to the development of small molecule inhibitors to Integrator, which may overcome the present therapeutic difficulties in targeting the MAPK pathway in cancer." (PMID 28982763, 2017).
neurodevelopmental disorder (3 papers, 2026). A behavioral and cognitive disorder with onset during the developmental period that involves impaired or aberrant development of intellectual, motor, or social functions. "Mutations in INTS11, the catalytic subunit of the Integrator complex essential for RNA processing and transcriptional termination, have been linked to neurodevelopmental disorders (NDDs), yet the underlying mechanisms remain poorly understood." (PMID 41837557, 2026).
neurological disorders (2 papers, 2025 to 2026). "Unlike dominant mutations in INTS6, biallelic mutations in other INTS genes, such as INTS11, are associated with neurodevelopmental or neurological disorders." (PMID 40966122, 2025).
infection (1 paper, 2025). The state of being infected such as from the introduction of a foreign agent such as serum, vaccine, antigenic substance or organism. "Similar phenotypes are observed in our primary infection to the lytic model, where a deficiency of INTS11 attenuates the production of KSHV lytic mRNAs and proteins." (PMID 40801543, 2025). "In contrast, INTS11 plays a minor role in latency following primary infection." (PMID 40801543, 2025). "Collectively, INTS11 is essential for optimal lytic replication of KSHV, either directly from primary infection or reactivation from the latent phase." (PMID 40801543, 2025). "We find that integrator subunit 11 (INTS11), the enzymatic core of INT, is essential for KSHV lytic replication triggered by reactivation or primary infection." (PMID 40801543, 2025).
INTS11 also shares sentences with these, for which no sentence is quoted: melanoma (3 papers); developmental delays (1); intellectual disabilities (1); microcephaly (1); neuron migration disorder (1); Retinal dystrophy (1); retinopathy (1).